MIF (macrophage migration inhibitory factor)
Diseases named in the same sentence as MIF in open-access papers (continued):
Sharing a sentence is not in itself a finding about the gene and the disease.
tumor (continued). "These gene-positive macrophages secreted factors such as TNF, TGFB1, and notably MIF, which is implicated in T cell suppression—suggesting a complex role of these macrophages in both propagating tumor growth as well as modulating the immune landscape to favor tumor immune escape." (PMID 40620715, 2025). "Specifically, AG activates tumor‐associated mast cells (TAMCs), reprogrammes myofibroblastic cancer‐associated fibroblasts (myCAFs) into inflammatory CAFs (iCAFs), and enhances suppressive crosstalk between TAMCs, iCAFs, and T cells via the macrophage migration inhibitory factor (MIF) axis." (PMID 41159485, 2025). "Cell-cell communications analysis in scRNA-seq and stRNA-seq identified ligand-receptor pairs of the CXCL, EGF, FGF, and MIF signaling pathways as bridges implying that tumor microenvironment may cause malignant cells’ transcriptomic adaptability and disease progression." (PMID 37397378, 2023). "Furthermore, plasma MIF can improve the diagnostic specificity for NPC patients combined with VCA-IgA, suggesting that high tumor-associated MIF expression may drive higher circulating levels of soluble MIF." (PMID 34407796, 2021). "By using microarray technology it was reported that in MIF-reduced NB cells there was a downregulation of certain genes associated with tumor development including IL-8 and C-met along with upregulation of the tumor-suppressor genes EPHB6, visinin-like protein 1 (VSNL-1), and BLU." (PMID 32155795, 2020). "Besides patients carrying a BRAF mutation, MIF inhibitors could technically be effective on many tumor types harboring different mutation profiles, providing therapeutic alternatives to patients whose tumors do not correspond to classical targeted therapies." (PMID 31013837, 2019). "Indeed, regarding the results of Girard’s studies, MIF ability to regulate tumor vascularization could also be linked to its ability to regulate the expression of pro-angiogenic chemokines and to modulate the recruitment and activity of pro-inflammatory cells." (PMID 31013837, 2019). "Therefore, we next asked whether loss of MIF expression was associated with a heightened anti-tumor immune response in vivo." (PMID 29864117, 2018). "Most of the studies in GBM actually indicate that local production of MIF might be associated with a milieu favoring tumor escape from immune surveillance and its action seems to be primarily, but not exclusively exerted, at the level of microglia cells and regulation of their functions." (PMID 29707160, 2018). "Since MIF has been identified as a gene up-regulated in tumor-promoting macrophages and associated with tumor progression and metastasis, the development of the non-viral nanoparticle system may lead to innovative therapeutic strategies targeting tumor microenvironment." (PMID 25799489, 2015). "Furthermore, tumor-associated angiogenesis examined by a Millipore chamber filled with colon-26 cells in the subcutaneous fascia of the flank of mice was significantly suppressed by the administration of anti-MIF antibodies." (PMID 23050964, 2012). "MIF has been implicated in metastasis via interactions with the CD44 receptor in laryngeal cancer, a marker of cancer stem cells that enhances tumor cell adhesion and migration." (PMID 41545340, 2026). "In these types of cancer, CD74 frequently co-localizes with MIF at the tumor-stromal interface, activating downstream signaling pathways that sustain tumor growth and metastasis." (PMID 41597203, 2026). "Validation in patient-derived metastatic liver tissues confirmed elevated hepatic MIF expression and increased CD44-positive tumor cells in MASLD-associated PDAC cases." (PMID 41545340, 2026). "The interaction of MIF with the tumor stroma further contributes to an environment that favors tumor progression and metastasis." (PMID 41597235, 2026).
tumor (continued). "MIF mediates its tumor-promoting effects through binding to CD74, thereby activating pathways such as PI3K/Akt, and stimulating angiogenesis via molecules such as VEGF and IL-8." (PMID 41597203, 2026). "MIF is secreted into the extracellular space in response to inflammatory stimuli or stress, where it influences tumor progression via autocrine and paracrine signaling mechanisms." (PMID 41597235, 2026). "Our immunohistochemistry data demonstrated high expression of both HMGCR and MIF in a subset of ESCC tumor cells." (PMID 41355948, 2026). "Mechanistically, tumor-derived MIF competitively inhibits CXCL12-CXCR4 binding—a canonical pathway essential for GC B cell affinity maturation 35—thereby impairing antibody-driven immunity." (PMID 41355948, 2026). "CD44, a glycoprotein regulating tumor stemness and adhesion, was functionally tested using recombinant MIF (rMIF)." (PMID 41545340, 2026). "Single-cell and spatial transcriptomic analyses showed that high-pyrimidine-metabolism tumor cells interact with immune cells via enhanced migration inhibitory factor (MIF) signaling." (PMID 42006371, 2026). "Beyond antibody-based strategies, small-molecule MIF inhibitors represent an additional approach to disrupt MIF-mediated tumor growth." (PMID 41597203, 2026). "Multiplexed immunofluorescence revealed that CHEK1 and MIF are co-expressed in tumor cells, and CHEK1-high tumor cells exhibit closer spatial proximity to M2-like macrophages." (PMID 41722056, 2026). "In contrast, MG3, MG4, and monocyte subsets 1 and 2—which were less concentrated within tumor cores—exhibited significantly weaker engagement with pro-tumor or immunosuppressive pathways, including MIF, TNF, IL-4, IL-6, OSM, galectin, and TGF-β." (PMID 41503214, 2026). "Elevated MIF in serum and tumor tissue correlates with tumor differentiation, lymph node involvement, and liver metastasis in CRC patients." (PMID 40835826, 2025). "Further cell communication analysis suggests that tumor epithelial cells and macrophages primarily interact through the MIF and IFN-II pathways." (PMID 41235252, 2025). "In another study it was reported that CPSI-1306 decreased both tumor development and neovascularization via blocking the enzymatic portion of MIF." (PMID 41159021, 2025). "Previous studies reported the role of MIF on suppressing the anti-tumor effect of NKs and inactivation of T cells in different solid tumors." (PMID 41159021, 2025). "Imalumab (BAX69) is a recombinant monoclonal antibody that specifically binds to the oxidized form of MIF (oxMIF) found in tumor tissues and inflammatory sites." (PMID 41472252, 2025). "The MIF factor released by tumor cells due to PKM2 can bind to the CXCR4 receptor on the surface of MDSCs and activate the MAPK pathway, thereby initiating the MEK-ERK signaling cascade." (PMID 40948745, 2025). "In summary, we have tailored a tumor cell GA‐targeting self‐assembled peptide (NF‐1) for effective immunotherapy via reshaping the MIF‐mediated immunosuppressive network." (PMID 39908165, 2025). "We found that MIF (CD74-CXCR4) and MIF (CD74-CD44) were significantly upregulated in tumor epithelial cells." (PMID 40424306, 2025). "MIF plays a key role in fundamental processes that control cell proliferation, differentiation, angiogenesis, and tumor progression 15,22-24." (PMID 40092701, 2025). "Cellular interaction and immunohistochemical analysis proposed MIF‐(CD74 + CXCR4) signaling pathway as a key mechanism by which malignant cells influence immune cells within the tumor microenvironment." (PMID 40018995, 2025). "Conversely, knockdown of MIF leads to anti-tumor effects of myeloid cells, which attributes to the reduction of SPP1+ macrophages that play roles in extracellular matrix remodeling." (PMID 39891284, 2025). "MIF, a pro-inflammatory cytokine, plays a crucial role in promoting immune escape and tumor progression within the tumor microenvironment through multiple mechanisms." (PMID 40315269, 2025).
tumor (continued). "Collectively, these findings establish MIF not only as a driver of tumor progression but also as a promising, though still underexploited, target for therapeutic intervention." (PMID 41159021, 2025). "MIF is frequently overexpressed across a broad range of malignancies, with its expression levels positively correlated with tumor progression." (PMID 41127012, 2025). "Ongoing studies to evaluate CD74 expressing immune populations and their unique contribution in the tumor microenvironment will be informative, particularly in response to MIF‐pathway inhibition." (PMID 40131169, 2025). "The ligand‐receptor interactions between tumor cells and major immune cell populations were mainly present in the MIF signaling pathway, with the ligand‐receptor pair MIF‐(CD74 + CXCR4) exerting the most significant influence on this pathway." (PMID 40018995, 2025). "Earlier studies have indicated that MIF exhibits various biological effects, including immune response regulation and influence on tumour cell proliferation." (PMID 40596746, 2025). "We then decided to delineate the M1 and M2 macrophage populations, with the expectation that this tumour would contain more M1 (pro-inflammatory) macrophages, because of the high expression of MIF." (PMID 41168392, 2025). "Given the potential of tumor- or host-derived MIF in affecting tumor growth and the immune response, we assessed tumor growth in MIF gene–knockout (Mif–/– or MIF-KO) mice." (PMID 41122966, 2025). "Focusing on the SSR4+ and SSR4- cell subtypes, SSR4 expression levels were closely related to the interaction patterns that existed between tumor plasma cells as well as other cell subtypes, especially in the MIF/CD74/CXCR4 pathway." (PMID 40066443, 2025). "These therapeutic proof-of-principle models highlight the critical role of tumor cell-intrinsic MIF and underscore its potential as a selective and actionable target for anti-cancer therapy in advanced CRC." (PMID 40835826, 2025). "A self‐assembled peptide (NF‐1) targeting tumor cell Golgi apparatus (GA) is tailored for effective immunotherapy via reshaping the MIF‐mediated immunosuppressive network." (PMID 39908165, 2025). "In TAMs, SPP1–CD44 and related integrin signals, key mediators of M2 polarization, were suppressed in PIAS1+ cells, while tumor-derived MIF signals promoting M1-polarizing were enhanced." (PMID 40941002, 2025). "This suggests that MIF functions switch from a proinflammatory cytokine to a tumor-specific chemokine and angiogenic-like factor during tumor progression." (PMID 40835826, 2025). "We and others have demonstrated that MIF is selectively elevated and stabilized in tumor cells, where it plays a critical role in driving tumor progression." (PMID 40835826, 2025). "Methionine restriction enhanced the M1-type polarization via suppressing MIF derived from tumor cells, highlighting a novel avenue for developing therapeutic drugs for GC." (PMID 40599798, 2025). "Macrophage migration inhibitory factor (MIF) is an upstream immunoregulatory cytokine that promotes transformed cell proliferation and survival, and generates a tumor‐permissive immune landscape of immunosuppressive myeloid and T cells." (PMID 40131169, 2025). "The results showed that, compared to the control group, MIF knockdown in SCC7 cells resulted in a reduction in tumor size, accompanied by a significant decrease in the number of both CD74+PDGFRB+ and FAP+ cells." (PMID 39891284, 2025). "MIF expression was predominantly present in malignant specimens, with most of the expression localized to the cytoplasm of tumor cells." (PMID 41159021, 2025). "ST analysis identified spatially restricted tumor–macrophage interactions mediated by macrophage migration inhibitory factor (MIF)." (PMID 40867511, 2025). "Among these interactions, macrophage migration inhibitory factor (MIF) plays a crucial role as a chemokine, promoting the secretion of potent T lymphocyte attractant by tumor vascular endothelial cells." (PMID 40575173, 2025).
tumor (continued). "Studies suggest that MIF contributes to immunosuppression by inhibiting cross presentation of tumor antigens by DCs to CD8+ T cells via MHC class I." (PMID 41159021, 2025). "Elevated MIF expression in tumor tissue, serum, or plasma often correlates with advanced disease stage, poor prognosis, and resistance to therapy." (PMID 41159021, 2025). "In conclusion, MIF regulates the production of immune suppressive factors by DCs and other immune cells that promote tumor growth." (PMID 41159021, 2025). "As anticipated, the expression level of MIF in tumor tissues was significantly upregulated compared to healthy tissues." (PMID 41210694, 2025). "MIF modulates the complex activities of NK cells, one of the primary elements of the innate immune response that directly kill tumor cells." (PMID 41159021, 2025). "Mechanistic studies show that MIF knockdown, via RNA interference (RNAi) or NF-κB inhibitor Parthenolide, reduces IL-8 expression and inhibits the growth of tumor spheres." (PMID 41472252, 2025). "In sum, this proof-of-principle experiment showed that epithelial, stabilized MIF is essential for tumor maintenance." (PMID 40835826, 2025). "This visualization underscores the intricate and vital role of MIF signaling in mediating cell–cell communication within the tumor microenvironment." (PMID 41008826, 2025). "Previous studies have demonstrated that MIF stimulates the development of Tregs by modulating IL-2 production, hence increasing tumor growth by generating an environment permissive to immunological tolerance." (PMID 41159021, 2025). "Targeting MIF can inhibit OS progression, enhance chemotherapy sensitivity, and exert anticancer effects by regulating the tumor microenvironment." (PMID 40895569, 2025). "Differential analysis of incoming and outgoing signals between myeloid and epithelial cells in normal and tumor tissues showed amplified MIF signaling from tumor epithelial cells and enhanced MIF reception in myeloid cells." (PMID 39891284, 2025). "Like NPC2, LY96 positive macrophages secrete MIF affecting T cells, inhibiting T cell activity, and mediating tumor immune escape." (PMID 40620715, 2025). "Both MIF and MIF-2 play critical roles in cancer progression, and their simultaneous inhibition has shown synergistic anti-tumor effects." (PMID 40835826, 2025). "The reduction in AcAc enhances the activity of the macrophage migration inhibitory factor (MIF), which ultimately leads to increased macrophage recruitment and promotes tumor growth." (PMID 39857793, 2025). "MIF is highly expressed in OS and promotes tumor proliferation and metastasis by activating the RAS/MAPK pathway, and is associated with poor prognosis." (PMID 40895569, 2025). "Please note that analysis of sufficient MIF ablations exposed stronger effects with a 57.9% reduction on tumor growth than TAM-treated tumors in the macroscopic analysis with a reduction of 33.3% compared to each oil groups." (PMID 40835826, 2025). "Several reports have identified that tumor-derived MIF can drive the expansion of both monocytic and granulocytic populations, thus enhancing the overall immunosuppressive capability of the tumor." (PMID 41159021, 2025). "Clinical evidence has shown that high levels of MIF are accompanied by higher levels and activity of MDSCs, an integral aspect of tumor immune survival." (PMID 41159021, 2025). "Similar survival outcomes were observed in the colorectal MC38 model, with most mice treated with anti–PD-1/anti-MIF exhibiting superior tumor rejection." (PMID 41122966, 2025). "MIF is expressed by both tumor and immune cells, and high MIF levels are found within and secreted from YUMMER1.7 and MC38 cells." (PMID 41122966, 2025). "For example, macrophage MIF promotes the progression of multiple tumor types by modulating the immune and inflammatory responses." (PMID 40092698, 2025).
tumor (continued). "The review also explores the molecular mechanisms of MIF involvement in tumor pathogenesis through promoting proliferation, angiogenesis, immune evasion, and metastasis." (PMID 41159021, 2025). "Additional studies are needed to fully understand early host-tumor contributions of MIF signaling and the benefit of adding anti–PD-1 therapy in this context." (PMID 41122966, 2025). "Reconstitution of tumors with varying ratios of MIF wild‐type and MIF KO clones led to corresponding changes in tumor volume." (PMID 40131169, 2025). "On the one hand, tumor cell C1_EGFR+ and C2_STAT1+ directly act on CD8T_GNLY+ through the MDK–(ITGA4+ITGB1) axis and the MIF–(CD74+CXCR4) axis to promote tumor proliferation." (PMID 40948762, 2025). "MIF serves as a crucial molecule in the tumor microenvironment that promotes tumor progression and mediates immune suppression." (PMID 40464813, 2025). "Since anti-MIF antibodies have demonstrated the ability to reduce tumor burden and enhance immune cell infiltration in preclinical studies, such approaches offer improved specificity compared to small molecule inhibitors." (PMID 41159021, 2025). "Co-expression of MIF and CD74, detected using factor VII staining, correlated with elevated levels of angiogenic CXC chemokines and greater tumor vascularity, which reinforces MIF’s role in promoting tumor angiogenesis." (PMID 41159021, 2025). "Tumor cells also express high levels of MIF, which enables malignant tumors to evade immune surveillance by inhibiting NK cell-mediated detection and clearance." (PMID 41181127, 2025). "In a resembling manner, TPP1 positive macrophages secrete MIF acting on T cells, thus inhibiting T cell activity and mediating tumor immune escape." (PMID 40620715, 2025). "As expected, oil-treated Miffl/fl;TP53Q/+ tumors exhibited a strong and equal MIF protein stabilization in the epithelial tumor part." (PMID 40835826, 2025). "Tumor areas of the TAM-treated group with a sufficient MIF depletion confirmed the reduction of cancer growth compared to the oil-treated groups." (PMID 40835826, 2025). "For instance, tumour exosome-derived migration inhibitory factor (MIF) has been shown to orchestrate the events involved in liver premetastatic niche formation during PDAC metastasis." (PMID 39863771, 2025). "This highlights the therapeutic selectivity of HSP90 inhibitors in targeting MIF-stabilized tumor cells." (PMID 40835826, 2025). "Receptor-ligand analysis further confirmed that tumor cells with high glycan scores exhibited stronger interactions with immune and stromal cells, particularly through MIF and MDK ligands." (PMID 40861802, 2025). "To further investigate the expression and role of MIF in CRC, we compared MIF expression levels between normal and tumor tissues." (PMID 40589755, 2025). "MIF promotes tumour growth and metastasis by enhancing myeloid cell activation and environmental adaptation." (PMID 40596746, 2025). "Ligand–receptor interaction mapping revealed that tumor-derived MIF and macrophage-expressed CD74 (with co-receptor CD44) form a signaling axis in ZDHHC9-high tumors." (PMID 40740766, 2025). "Low and high neoplastic are in multiple tumor malignant progression-related pathways such as MIF, ITGB2, and FN1 with different cells for messaging." (PMID 40303412, 2025). "MIF plays a role in various biological functions, such as leukocyte recruitment, inflammation, immune responses, cell proliferation, tumor development, and the counter-regulation of glucocorticoids in both physiological and pathological processes." (PMID 41159021, 2025).